FGF21 (fibroblast growth factor 21)
Diseases named in the same sentence as FGF21 in open-access papers (continued):
Sharing a sentence is not in itself a finding about the gene and the disease.
non-alcoholic fatty liver disease (91 papers, 2011 to 2026). "The function of FGF21 in metabolic health in relation to protein intake levels was demonstrated by analyzing FGF21 polygenic scores for the risk of non-alcoholic fatty liver disease." (PMID 38257122, 2024). "FGF21 plays a pivotal role in modulating inflammatory responses, as evidenced by the development of various inflammatory disorders in FGF21-deficient conditions, including non-alcoholic fatty liver disease (NAFLD) and pancreatitis." (PMID 40231082, 2025). "Moreover, FGF-21 protects against non-alcoholic fatty liver disease (NAFLD) and the stress caused by the metabolic disorders in the liver." (PMID 33924457, 2021). "Circulating fibroblast growth factor-21 levels were higher in patients with nonalcoholic fatty liver disease compared to controls." (PMID 40465044, 2025). "FGF21 is considered a protective agent from nonalcoholic steatohepatitis and nonalcoholic fatty liver disease." (PMID 39452947, 2024). "In this study, we investigated the regenerative potential of chimeric FGF21/HGFR as a therapeutic strategy for non-alcoholic fatty liver disease (NAFLD)." (PMID 38542065, 2024). "This step would further contribute to a comprehensive understanding of the therapeutic potential of chimeric FGF21/HGFR in the context of non-alcoholic fatty liver disease." (PMID 38542065, 2024). "A study showed that pharmacological administration of sulforaphane can increase the expression of FGF21 and reduce the phosphorylation level of p38 in liver, thus improving nonalcoholic fatty liver disease." (PMID 36742397, 2023). "MiR-149 controls non-alcoholic fatty liver disease by targeting FGF-21; it also inhibits the ATF6 pathway to reduce inflammation and apoptosis in nonalcoholic fatty liver disease brought on by endoplasmic reticulum stress." (PMID 37259030, 2023). "FGF-21 is increased in obese patients, and it is correlated with the hepatic fat content and with the nonalcoholic fatty liver disease activity score." (PMID 37999211, 2023). "Fibroblast growth factor 21 (FGF-21), previously recognized as a marker of liver damage and a potential drug target in non-alcoholic fatty liver disease (NAFLD), has unclear implications in hepatitis C virus (HCV) infections." (PMID 37999215, 2023). "Co-citation cluster labels revealed characteristics of ten main clusters: non-alcoholic fatty liver disease, gut microbiota, adiponectin, fructose, fgf21, fatty acid, liver x receptor, nr4a, obese mice, and bile acids." (PMID 35911114, 2022). "Fibroblast growth factor 21 (FGF21) signaling and genetic factors are involved in non-alcoholic fatty liver disease (NAFLD) pathogenesis." (PMID 35630668, 2022). "Our previous study demonstrated that hepatic STAMP2 mediates recombinant FGF21-induced improvements in hepatic iron overload in nonalcoholic fatty liver disease through the upregulation of expression of the iron exporter, ferroportin." (PMID 36140186, 2022). "Fibroblast growth factor 21 (FGF21) is a circulating protein primarily secreted by the liver that lowers blood glucose levels, corrects abnormal lipid profiles, and mitigates non-alcoholic fatty liver disease." (PMID 34046014, 2021). "Circulating FGF21 levels are highly elevated in non-alcoholic fatty liver disease (NAFLD) patients, as well as, in obese animals, suggestive of impaired FGF21 signaling." (PMID 32042044, 2020). "Elevated serum FGF21 concentrations were also correlated with hepatic fat content in subjects with non-alcoholic fatty liver disease." (PMID 30185439, 2018). "Fibroblasts growth factor 21 (FGF21), a liver-secreted endocrine factor involved in regulating glucose and lipid metabolism, has been shown to be elevated in patients with non-alcoholic fatty liver disease (NAFLD)." (PMID 21949781, 2011). "Furthermore, sweroside improves nonalcoholic fatty liver disease in mice by modulating the expression of the Cd36 and Fgf21 genes, thereby impacting lipid metabolism and the inflammatory response." (PMID 41282626, 2025).
non-alcoholic fatty liver disease (continued). "Moreover, FGF21 is a potential therapeutic target in non-alcoholic fatty liver disease, and clinical trials on FGF21 in this condition have reported favourable results." (PMID 40242310, 2025). "The efficacy of using FGF21-164 to reduce hepatic fat accumulation in DIO mice suggested that it may help treat non-alcoholic fatty liver disease (NAFLD)." (PMID 40141314, 2025). "Elevated FGF21 levels are observed in early-stage non-alcoholic fatty liver disease (NAFLD)." (PMID 41440753, 2025). "Indeed, FGF21 analogs have demonstrated a favorable pharmacological profile in reversing non-alcoholic fatty liver disease and its more severe stages, such as steatohepatitis." (PMID 39409124, 2024). "However, ERS induced by skeletal muscle exercise can increase the release of muscle factors such as Fibroblast growth factor 21 (FGF21) and IL-6, ultimately reducing liver IR in non-alcoholic fatty liver disease." (PMID 38542170, 2024). "Further, dysregulated FGF21 levels are affiliated with certain metabolic diseases such as liver diseases (e.g., nonalcoholic fatty liver disease and nonalcoholic steatohepatitis, liver fibrosis), obesity, diabetes, cardiovascular diseases (e.g., atherosclerosis), and cancer." (PMID 39766329, 2024). "Recently, evidence has accumulated that Gadd45b deficiency promotes premature aging and skin senescence, and FGFR1 has been reported to ameliorate impaired lipid metabolism in mice with non-alcoholic fatty liver disease through upward regulation of the FGF21/FGFR1 pathway." (PMID 37958806, 2023). "FGF21 can inhibit the progression of nonalcoholic fatty liver disease." (PMID 36742397, 2023). "FGF21; Fertility; Non-alcoholic fatty liver disease; High-fat diet." (PMID 36406708, 2022). "Also, fibroblast growth factor 21 (FGF21) has essential functions in liver metabolism and is also a potential marker for nonalcoholic fatty liver disease (NAFL)." (PMID 34651050, 2021). "Regarding this effect, a clinical trial has been studied using a novel long-acting FGF21 pegbelfermin which may have therapeutic effects on nonalcoholic fatty liver disease and nonalcoholic steatohepatitis." (PMID 34502311, 2021). "Similarly, a positive relationship of serum FGF21 levels with liver lipid content and Body Mass Index (BMI) and an inverse relationship of FGF-21 with serum adiponectin levels were found in non-alcoholic fatty liver disease (NAFLD) patients." (PMID 26497746, 2015). "Interestingly, prior studies found raised serum FGF21 levels in patients with non-alcoholic fatty liver disease, a metabolic liver disease supporting further investigation of this ligand in the pathogenesis of liver disease." (PMID 24848261, 2014). "Notably, the dysregulation in FADS1 influences hepatic lipid homeostasis by modulating the PPARα-FGF21 axis and a decreased hepatic FADS1 expression, associated with low levels of long-chain PUFAs, have been detected in subjects with nonalcoholic fatty liver disease (NAFLD)." (PMID 36140410, 2022). "Serum FGF21 level varies with different physiologic and pathological status, such as starvation, obesity, diabetes, and non-alcoholic fatty liver disease (NAFLD) as well." (PMID 30692965, 2018). "This step would contribute to a more comprehensive understanding of the regenerative properties of chimeric FGF21/HGFR and its potential as a therapeutic intervention for non-alcoholic fatty liver disease in humans." (PMID 38542065, 2024). "In mouse models of non-alcoholic fatty liver disease (NAFLD) and NASH, FGF21 and its analogs have been shown to act as hepatoprotective factors by directly regulating hepatic lipid and free fatty acid metabolism." (PMID 38962005, 2024). "Preclinical studies have suggested that FGF21 induction exerts a protective effect against non-alcoholic fatty liver disease (NAFLD), while human studies have revealed elevated levels of and potential resistance to FGF21 in patients with NAFLD." (PMID 37242268, 2023).
non-alcoholic fatty liver disease (continued). "Fibroblast growth factor 21 (FGF21) and cytokeratin 18 (CK18) were previously reported to be elevated in nonalcoholic fatty liver disease (NAFLD)." (PMID 28698650, 2017). "The expression of FGF-21 and PGC-1α is upregulated in mice, suggestive of non-alcoholic fatty liver disease, but FGF-21 does not appear to be similarly expressed in poultry." (PMID 40284594, 2025). "In diabetic women, subjects with LEAD had significantly higher serum FGF21 regardless of non-alcoholic fatty liver disease (NAFLD) (P < 0.05)." (PMID 25850006, 2015).
Hypertension (77 papers, 2010 to 2026). The presence of chronic increased pressure in the systemic arterial system. "Our study fills a void and confirms the association between FGF21 and hypertension in Asian population." (PMID 40356318, 2025). "Due to the nature of cross-sectional study, it inevitably avoids determining the causal relationship between FGF21 and hypertension." (PMID 40356318, 2025). "The association of FGF21 with BP and hypertension in our study supports the concept of FGF21 resistance." (PMID 40356318, 2025). "In the sensitivity analysis, ln-transformed FGF21 was associated with hypertension after excluding participants who had hypertensive medication." (PMID 40356318, 2025). "Serum FGF21 level was associated with hypertension (quartile 4 vs. quartile 1, OR = 4.19 [95% CI 2.65–6.61]; p for trend < .001)." (PMID 40356318, 2025). "Based on the findings from our preclinical study and possible underlying mechanisms, it is reasonable to understand that FGF21 is a biomarker for hypertension in this study, which is conducted in human beings." (PMID 40356318, 2025). "Higher serum FGF21 level was associated with higher risk of hypertension (quartile 4 vs. quartile 1, OR = 4.19 [95% CI 2.65–6.61]; p for trend <.001)." (PMID 40356318, 2025). "A marked change in the odds ratio of serum FGF21 at hypertension risk occurred in the 113.3–544.6 pg/mL range (ln-transformed FGF21, 4.7–6.3; estimate from the spline)." (PMID 40356318, 2025). "What’s more, this experiment also found that FGF-21 was associated with TG levels, and hypertension." (PMID 35574015, 2022). "Evidence from clinical studies identified an association between elevated circulating FGF21 and hypertension." (PMID 32858953, 2020). "Clinical studies have shown an association between hypertension and the circulating levels of fibroblast growth factor 21 (FGF21), tumour necrosis factor superfamily member 14 (TNFSF14) and tumour necrosis factor-α (TNF-α)." (PMID 32858953, 2020). "Our data suggest that FGF21-induced water intake is in fact secondary to diuresis, which we propose to be a compensatory mechanism engaged to alleviate the acute hypertension caused by FGF21." (PMID 30106981, 2018). "In summary, our data suggest that FGF21-induced water intake is in fact secondary to diuresis, which we believe is a compensatory mechanism engaged to alleviate the hypertension caused by our FGF21 analog." (PMID 30106981, 2018). "The unadjusted PheWAS analysis, however, revealed that higher FGF21 levels were also associated with increased height, waist circumference, hypertension, high creatinine levels, the use of statins, and the use of ace inhibitors among other clinical variables." (PMID 25664662, 2015). "In conclusion, FGF21 is associated with BP and hypertension." (PMID 40356318, 2025). "The association between FGF21 and hypertension was found in US adults." (PMID 40356318, 2025). "A robust association between FGF21 and hypertension was also found in the fully adjusted model." (PMID 40356318, 2025). "Additionally, associations with adiponectin, high blood pressure, BMI, age, and kidney function further highlight the complex interplay between FGF21 and diverse physiological factors under metabolic strain." (PMID 39194718, 2024). "The association between FGF21 and hypertension has also been observed in animal models." (PMID 37576954, 2023). "Previous studies have shown that FGF21 in serum was associated with cardiovascular diseases such as diabetic cardiomyopathy, hypertensive heart disease, atrial fibrillation, coronary artery disease, and hypertension." (PMID 35069790, 2022). "However, FGF21 was still capable of causing hypertension in animals in which approximately 40% of the sympathetic post-ganglionic neurons were ablated." (PMID 30106981, 2018). "FGF21 has been independently positively associated with hypertension in a community sample." (PMID 25890271, 2015). "The elevated serum FGF21 was reported to associate with hypertension." (PMID 25823710, 2015).
Hypertension (continued). "Although the use of the FGF21 analogue has not been applied in patients with hypertension, based on the mechanisms between FGF21 and BP, FGF21 is a promising therapeutic target for treating hypertension." (PMID 40356318, 2025). "FGF21 derived from brown adipose tissue has been found to lower BP and protect against hypertension." (PMID 40356318, 2025). "The odds ratio of hypertension increased slowly but steadily among those with serum FGF21 above 544.6 pg/mL." (PMID 40356318, 2025). "The plot shows a slight decrease in odd ratio of hypertension within the lower range of ln-transformed FGF21." (PMID 40356318, 2025). "FGF21 specifically of BAT origin protects the heart from maladaptive remodeling in hypertension, myocardial ischemia/reperfusion injury, and acute myocardial infarction." (PMID 40149686, 2025). "The relationship between FGF21 and hypertension in the Asian population is unclear and therefore further investigation is needed." (PMID 40356318, 2025). "In an animal model of hypertension, angiotensin-II induces FGF21, which has a compensatory response to hypertension by angiotensin-converting enzyme II, which inactivates angiotensin-II." (PMID 38750219, 2024). "FGF21 presented a positive association with the prevalence of RAO in the crude model and mode l (adjusted for clinical data such as sex, age, diabetic and hypertension)." (PMID 38789571, 2024). "There are limited studies investigating the relationship of Cluster of differentiation 56 (CD56), A disintegrin and metalloprotease 17 (ADAM17) and Fibroblast growth factor 21 (FGF21) with hypertension and PE." (PMID 37374349, 2023). "FGF21 released from brown adipose tissue ameliorated cardiac fibrosis and hypertension-induced myocardial remodeling." (PMID 37416922, 2023). "FGF21 levels were significantly increased in the liver, heart, and serum in a mouse model of angiotensin II-induced hypertension compared to the control group." (PMID 37576954, 2023). "Elevated FGF21 levels in patients with type 2 diabetes were positively correlated with hypertension, hyperglycemia, glycated hemoglobin, insulin resistance, and high-sensitivity C-reactive protein levels." (PMID 35677107, 2022). "Serum levels of FGF21 and vWF are increased in elderly patients with hypertension and comorbid CAS, so they can be used for diagnosing CAS and predicting prognosis." (PMID 35242298, 2022). "The univariate Cox analysis showed that serum FGF21, BNP, creatinine, age, sex, hypertension, LVEDD, and LVEF were associated with a poor prognosis." (PMID 35069790, 2022). "Subjects with FGF-21 levels of ≥1.40 pg/dl had greater portion of hypertension, albuminuria, or advanced CKD but the uses of RAS blockade were also more common comparing with those with FGF-21 < 1.40 pg/dl (56% vs 41%, p = 0.009)." (PMID 35528011, 2022). "In a hypertension model induced by Ang II treatment for one week, Fgf21−/− mice developed a greater degree of extensive cardiac dysfunction and fibrosis." (PMID 35677107, 2022). "Recent studies also identified FGF-21 as a biomarker for a variety of human diseases, including metabolic disorders 10, drug-induced liver injury 11, hypertension 12, and mitochondrial disease." (PMID 33537089, 2021). "Meanwhile, the proportion of HD patients with hypertension in high serum FGF21 level group is less than that in low serum FGF21 group (P < 0.05)." (PMID 34011291, 2021). "The incidences of overall CVDs (OR = 2.10, 95% CI: 1.09–4.06, p = 0.03) and hypertension (OR = 4.75, 95% CI: 3.55–6.37, p < 0.001) were significantly higher in individuals with higher FGF21 levels." (PMID 34513950, 2021). "Experiments in several mouse models of hypertension demonstrated that FGF21 can prevent or ameliorate hypertension." (PMID 32858953, 2020). "The A allele at FGF21, associated with lower total body-fat percentage and higher WHR was also associated with higher blood pressure, hypertension, and blood pressure medication use." (PMID 29641994, 2018).